MET (MET proto-oncogene, receptor tyrosine kinase)
Diseases named in the same sentence as MET in open-access papers (continued):
Sharing a sentence is not in itself a finding about the gene and the disease.
tumor (continued). "Interestingly, the receptor tyrosine kinase MET is induced by tumour-derived tumour necrosis factor-α or other inflammatory stimuli in human neutrophils." (PMID 34056114, 2021). "In the present study, a significant increase in MET expression was observed after first-line therapy, and it is possible that tumor cells that overexpress MET may be more resistant to chemotherapy." (PMID 34557411, 2021). "It is thought that overexpression of MET may facilitate the formation of CSCs from normal stem cells in the tumour microenvironment, or alternatively may encourage the de-differentiation of mature cells." (PMID 33526881, 2021). "Taken together, these results suggest that cabozantinib treatment drastically increased tumor-associated hypoxic stress, and tumor growth inhibition likely occurred independent of MET pathway inhibition in the LuCaP 93 PDX model." (PMID 33471819, 2021). "Furthermore, siRNA targeting ITGB1 efficiently alleviated the phosphorylation and protein maturation of MET, which triggers tumor formation and growth." (PMID 34977001, 2021). "Pharmacokinetics and circulating VEGF, VEGFR2, HGF, and MET levels were evaluated in patients taking the combination of pazopanib and tivantinib; tumor pharmacodynamic responses were assessed in patients receiving only pazopanib for 7 days prior to initiating combination therapy." (PMID 34180036, 2021). "Our results demonstrate that miR-34a directly targets MET and maintains anti-tumor immune activity." (PMID 33596979, 2021). "Blocking VEGF signaling may restore MET pathway activity as a compensatory signaling, leading to tumor recurrence with a more invasive phenotype." (PMID 34806012, 2021). "However, several other receptors and pathways are involved in tumor angiogenesis: FGFRs, PDGFRs, transforming growth factor-beta receptor (TGFβR), and hepatocyte growth factor receptor (HGFR, most known as MET), just to name a few." (PMID 34572729, 2021). "The results showed that the expression of MET in the tumour tissues of PDAC patients was significantly higher than that in the normal tissues, and the Kaplan-Meier analysis showed that high MET expression was correlated with a significant reduction in overall survival." (PMID 33816276, 2021). "When considering the mean expression levels of all tumor biopsies, all patients showed at least a two-fold increased expression in ESCC compared with non-tumor surrounding tissue, but only two out of five cases presented increased expression of MET in all individual regions of the tumor." (PMID 34037097, 2021). "Particularly, Capmatinib, a c-MET kinase inhibitor approved by the FDA to treat metastatic NSCLC with specific mutations, has shown to promote an anti-tumor response independent of the tumor cell-intrinsic c-MET pathway blockade." (PMID 34830850, 2021). "Consistent with the fact that MET is a transmembrane RTK, we also observed in both diagnostic biopsies and P/D specimens that the expression of MET was predominantly in the membrane of tumor cells, though a certain positivity was also visible to a lesser extent in the cytoplasm." (PMID 34884673, 2021). "Cough medications, including compound methoxyphenamine capsules, codeine phosphate, or montelukast showed no efficacy, On May 11, delayed next generation sequencing reported a 9.2-fold c-MET amplification in plasma levels and 4.4-fold in tumor tissue levels." (PMID 34516491, 2021). "c-MET expression is prevalent at the invasive front of the tumor, where the neoplastic cells interact with HGF expressing cancer-associated fibroblasts and macrophages, inducing cell growth and survival, cell motility, and tumor metastasis." (PMID 33562604, 2021). "In conclusion, MET inhibitors are used to target c‐MET expressing tumours." (PMID 34428346, 2021). "Currently, controversy does exist regarding the mechanism of action of tivantinib and whether a selective c-MET inhibition is the major anti-tumor effect of the drug." (PMID 34804015, 2021).
tumor (continued). "In addition, MET/HGF signaling protects tumour cells from DNA damage by activating the PI3K/AKT pathway." (PMID 34761497, 2021). "Moreover, c-MET expression in metastatic tissues was significantly higher compared with the primary tumor." (PMID 33466394, 2021). "Two out of five patients showed MET overexpression (at least two-fold change) in all tumor regions." (PMID 34037097, 2021). "Capmatinib (INC280), an efficient and specific MET suppressor, is a promising anti-tumor drug." (PMID 34479614, 2021). "In addition, mice bearing the MET-inhibitor-resistant GBM orthotopic xenografts treated with both COX-2 or FGFR and MET inhibitors exhibited enhanced MET sensitivity that correlated with significant inhibition in tumor growth." (PMID 34055785, 2021). "Eventually the HGF-c-MET system confers tumor progression and metastasis." (PMID 34257586, 2021). "Notably, MET+/RET+ LuCaP 93 and MET-/RET- LuCaP 173.1 tumor volumes were significantly decreased with cabozantinib treatment in vivo, and this activity was independent of MET or RET expression in LuCaP 173.1." (PMID 33471819, 2021). "Moreover, LMWF enhanced the suppressive effects of 5-FU on tumor cell migration through the c-MET/matrix metalloproteinase (MMP)-2 signaling pathway in both HCT116 and Caco-2 cells." (PMID 34360807, 2021). "Consistently, MET up-regulation was markedly correlated to tumor grade and T stage." (PMID 33869254, 2021). "Genes related to cancer pathways were downregulated upon atezolizumab treatment, including angiogenic factors for tumor vascularization (TNK1, AREG and KDR), proto-oncogenes (RET and MET) and tumor cell survival/migration/invasion (CDH1, RARA, WNK2, WNT4A, WNT9A, TGFB2, EGF, and LAMA3)." (PMID 32616706, 2020). "In addition, IHC staining showed that MET expression was significantly higher in NSCLC tumor tissues than in peritumoral tissues, as expected." (PMID 32614785, 2020). "Production of Indoleamine-2,3-dixoygenase (IDO) by tumor cells is another pathway by which the c-MET-HGF axis may contribute to an immunosuppressive tumor microenvironment." (PMID 32117721, 2020). "Therefore, HGF is distributed in cancer tissues mainly as scHGF, and MET activation occurs in cells in the close vicinity of tcHGF generated in the tumor microenvironment." (PMID 33121208, 2020). "In addition selective inhibition or SiRNA knockdown of c-MET decreased the viability of non-small cell lung cancer (NSCLC) cells demonstrating the direct effects of c-MET in promoting tumor growth." (PMID 32117721, 2020). "Collectively, our data may represent a new therapeutic approach for GC thought co‐inhibition of c‐MET and PARP, especially for patients with BRCA1/2 deficiency tumours." (PMID 32686903, 2020). "Thus, the antibody inhibits the activation of HGF/MET axis downstream signaling and tumor growth, and reduces the release of the inflammatory factor IL-6, thus suggesting a vast therapeutic potential." (PMID 32435640, 2020). "Thus, the typical way of identifying those patients who would be candidates for such targeted anti-cancer treatment is to evaluate MET expression/over-expression and activation in tumour tissue samples." (PMID 33149187, 2020). "Cell-specific knockdown of c-MET expression in neutrophils also enhanced the effectiveness of adoptive T-cell therapy, reducing recruitment of reactive neutrophils and increasing survival of tumor reactive T-cells." (PMID 32117721, 2020). "MET deletion in neutrophils leads to the enhancement of tumor growth and metastasis." (PMID 32435640, 2020). "In addition, MET protein expression in those tumor samples, as measured by IHC, was relatively low despite increased MET gene copy numbers." (PMID 31776899, 2020). "As a result, c-MET presents an attractive therapeutic target as there are clinically available inhibitors which may modulate the ability of cancer cells to evade anti-tumor immune responses." (PMID 32117721, 2020).
tumor (continued). "It has been proposed that members of the HER family of RTKs, especially HER2 or HER3, could compensate for a reduced MET function, thus contributing to tumor resistance against MET inhibitors." (PMID 33374770, 2020). "Nevertheless, taking into account the limited follow-up of the patients and the heterogeneity of MET overexpression found within the different tumor types and the technologies, the real clinical value of the assessment of MET expression in CTCs must be evaluated also in a larger cohort of patients." (PMID 32102486, 2020). "CXCR4+MET+CD44+ cells amounted to 2.2% of total tumor cells on average (range: 0.2–11%)." (PMID 32066735, 2020). "Upon interacting with c-MET, integrins ultimately enhance tumor cell invasiveness." (PMID 32175278, 2020). "Once overloaded, mitochondrial reactive oxygen species (ROS) inhibits mTOR activity and OXPHOS performance to prevent mitochondrial dysfunction-induced tumor cell death, by disrupting MET dimerization to block its autophosphorylation and interaction with vacuolar ATP synthase (V-ATPase)." (PMID 33377662, 2020). "Even at an advanced disease stage, a two-pronged approach, targeting (a) HGF/c-MET with relevant inhibitors and (b) cancer cells with chemotherapy, completely eliminated metastasis and significantly decreased tumour growth, suggesting that this is a promising treatment approach for PC." (PMID 32203220, 2020). "With regard to fibrosis, collagen deposition was largely unaffected by the treatments, except interestingly, the HGF-neutralising antibody + c-MET inhibitor (Hi + Ci)-treated tumours, which showed a significant decrease in collagen content when compared with those treated with gemcitabine alone." (PMID 32203220, 2020). "FACS revealed a distinct population of CXCR4+MET+ cells in patient’s tumor which could be further sorted into CD44+ and CD44− cells." (PMID 32066735, 2020). "For instance, tumor cells release MET+-exosomes that target endothelial progenitor cells." (PMID 32555170, 2020). "In the GEPIA dataset, only MET mRNA expression was significantly elevated in tumor samples." (PMID 33226369, 2020). "PD-L1 expression occurs more frequently with MET activation in NSCLC, suggesting that besides its well-characterized direct anti-tumor effects inhibition of c-MET signaling may act indirectly to alleviate immunosuppression." (PMID 32117721, 2020). "Endothelial cell-specific knock-out of MET was found to inhibit vascular transformation, result in the normalization of blood vessels, reduce intratumoral hypoxia, leading to suppressed tumor growth and prolonged survival in GBM-bearing mice following TMZ treatment." (PMID 35582224, 2020). "However, in a study where tumor samples with MET exon 14-alterations were available for assessment of PD-L1 status, outcomes with PD-1 blockade were poorer than for unselected patients." (PMID 32117721, 2020). "Moreover, they also confirmed that the down-regulation of LRRK2 in cultured tumor cells compromises MET activation and selectively reduces downstream MET signaling to mTOR and STAT3." (PMID 32196072, 2020). "This study was initially based on the hypothesis that INC280 and buparlisib would have a synergistic anti-tumor activity in recurrent glioblastoma with concomitant MET and PI3K activation." (PMID 31776899, 2020). "MET was originally identified as an oncogene that displayed 7-fold increased expression levels in PC samples, and its overexpression directly correlated with tumor grade and an aggressive PC phenotype." (PMID 33363572, 2020). "Importantly, the loss of miR-34a in OSA is associated with shorter disease-free survival times and an overexpression of its different target genes involved in tumour formation, such as MET, SIRT1, and CDK6." (PMID 33008041, 2020).
tumor (continued). "Moreover, the majority of commercially available cell lines exhibit high expression of c-MET and hence the response of orthotopic tumours produced by other cell lines + PSCs, would be reasonably expected to be similar to our findings with the current model." (PMID 32203220, 2020). "In addition to the lack of a ligand, activation of c-MET on cancer cells and endothelial cells in both primary tumour and metastatic nodules is prevented by the c-MET inhibitor." (PMID 32203220, 2020). "In this study, we found VEGFR3, MET and SLUG expression on cells derived from CIN3/cancer in situ/cancer stage IA tissue samples to be associated with the proportion of tumor infiltrating lymphocytes, with VEGFR3 and MET showing negative correlation and SLUG showing positive correlation with %TILs." (PMID 32899940, 2020). "MET may mediate its effects through actions on different cells of the tumor microenvironment, including MOs-macrophages that would be involved in controlling tumor cell growth and progression." (PMID 33108409, 2020). "Additionally, a few studies have shown that the kinase activity of the proviral integration site for Moloney murine leukemia virus (PIM) is required to acquire resistance to MET inhibitors in the MET-dependent tumor model." (PMID 32435640, 2020). "In addition, some clinical trials are being conducted based on the high MET expression and the mutations of RAS in tumor cells to find the potential biomarkers for predicting advanced HCC." (PMID 32420386, 2020). "Furthermore, miR-155 and miR-21 expression levels are significantly correlated with CRC, and miR-1 functions as a tumor suppressor in CRC by downregulating the MET oncogene." (PMID 32731413, 2020). "In addition, hypoxia is a characteristic of the tumor microenvironment and is closely related to resistance to MET-targeted inhibitors." (PMID 32435640, 2020). "If a relationship between c-MET inhibitors and PD-L1 expression is found in patient samples, then this could suggest that addition of c-MET inhibitors could also affect tumor immunity." (PMID 32117721, 2020). "As this FP result was not evaluated with other ctDNA methodology as a reflex test, the MET exon 14 could be due to the heterogeneity of the tumor." (PMID 33043062, 2020). "Cabozantinib (CBZ) is a tyrosine kinase inhibitor (TKI) that downregulates the activation of multiple receptor tyrosine kinases involved in tumor angiogenesis, invasion, and metastasis, including hepatocyte growth factor receptor (MET) and vascular endothelial growth factor receptor 2 (VEGFR2)." (PMID 32655941, 2020). "However, significantly decreased cancer cell numbers (due to decreased proliferation as well as increased apoptosis) were observed in tumours treated with gemcitabine alone or in dual or triple combinations with HGF/c-MET inhibitors." (PMID 32203220, 2020). "The increase in tumor invasiveness and metastasis in response to AI-induced hypoxia from anti-angiogenic therapies can be explained by the over-expression of the tyrosine protein kinase, c-MET." (PMID 32175278, 2020). "Moreover, the induction of apoptosis and cell cycle arrest exclusively existed in MKN45 cells, which demonstrated the exquisite ability of MET to drive tumor cell proliferation and mitogenesis." (PMID 34766112, 2020). "Furthermore, we evaluated two approaches to detect the presence of MET on circulating tumor cells (CTCs), using the CellSearch® and Parsortix systems and monitored patients under anti-EGFR treatment (n = 30) combining both cfDNA and CTCs analyses." (PMID 32102486, 2020).
tumor (continued). "The c-MET gene encodes the “c-MET tyrosine kinase” which induces metastasis and tumor invasion, and may play an important role in therapeutic resistance." (PMID 35047986, 2020). "We showed that BsAb-5 could inhibit HGF-mediated tumor development, serving as an inhibitory c-MET antibody." (PMID 29187584, 2019). "MET is a pivotal tyrosine kinase that promotes tumorigenesis and tumor metastasis." (PMID 31645479, 2019). "Moreover, a recent report showed that an HGF neutralizing antibody and a small c-MET inhibitor combined with gemcitabine greatly reduced tumor size in an orthotopic mouse model of PDAC." (PMID 31072019, 2019). "Interestingly, a high number of MET high-level amplified cases (n = 12) showed a subclonal MET amplification with high heterogeneity among the tumor cells." (PMID 30459450, 2019). "Furthermore, since Met overexpression and MET amplification has been implicated in acquired resistance to EGFR inhibition, we examined Met expression in MGG70R and MGG70RR patient tumour specimens and the respective GSC tumours." (PMID 30644426, 2019). "Validation with RNA-seq data of blood platelets shows that DDR achieves the superior performance in classification of six different tumor types as well as molecular target statuses (such as MET or HER2-positive, and mutant KRAS, EGFR or PIK3CA) with smaller sets of biomarkers." (PMID 31752658, 2019). "Dysregulation of cMet signaling–mediated proliferation, apoptosis, and migration through cMet overexpression, MET amplification, MET mutation, or HGF‐induced activation has been widely demonstrated in oncogenic processes across multiple tumor types, including NSCLC." (PMID 31040125, 2019). "The aim of this study was to address whether the increased tumor burden in Tpl2−/− mice is due to aberrant HGF/MET signaling." (PMID 30631034, 2019). "This enables the hepatocyte growth factor (HGF), also driven by the tumor, to bind to MET." (PMID 31474975, 2019). "This network demonstrates that 61 exosomal molecules may affect tumor progression through pathways controlled by key components including MET, Ras, RAF1, Mek, ERK1/2, MITF, BCL2, PI3K, Akt, mTOR, PD-1, KIT, JAK STAT3, or ETS1." (PMID 31681332, 2019). "Thus, AKT/c-MET tumor bearing mice were treated with PD901, either alone or in combination with MLN0128." (PMID 31277283, 2019). "In summary, LINC00857 influenced tumor cell proliferation, colony formation, apoptosis, as well as migration and invasion which may be via affecting MET/STAT3/c-Myc/CREB oncoproteins." (PMID 31085800, 2019). "Capmatinib (INC-280) is a c-MET inhibitor with anti-tumour activity in mouse models." (PMID 31308358, 2019). "Next, we treated the AKT/c-MET tumor bearing mice with regorafenib." (PMID 31277283, 2019). "MET-amplified tumor cells normally exhibit ligand-independent, constitutive MET activation." (PMID 30941314, 2019). "c-MET is known to activate cancer cell proliferation, migration and tumor invasiveness." (PMID 30871613, 2019). "Therefore, this study relied on assessing the pharmacodynamics of OC in EF-2 by quantifying and comparing the activated and total c-MET levels in EF-2-treated and placebo-treated control tumor cell lysates." (PMID 31590382, 2019). "We showed that BsAb-5 could inhibit hepatocyte growth factor (HGF) mediated tumor development, including proliferation, migration, and apoptosis, serving as an inhibitory c-MET antibody." (PMID 29187584, 2019). "Moreover, the disseminating tumor cell clusters boost metastatic colonization of the lungs via MET, as exemplified by attenuated ZEB1 expression." (PMID 31331982, 2019). "Taken together, LINC00857 affecting tumor cell proliferation, colony formation, apoptosis, as well as migration and invasion may be via MET, STAT3, c-Myc and CREB oncoproteins." (PMID 31085800, 2019).